NECTIN3 (nectin cell adhesion molecule 3)
Description:
Cell adhesion molecule that promotes cell-cell adhesion through heterophilic trans-interactions with nectins-like or other nectins, such as trans-interaction with NECTIN2 at Sertoli-spermatid junctions. Trans-interaction with PVR induces activation of CDC42 and RAC small G proteins through common signaling molecules such as SRC and RAP1. Induces endocytosis-mediated down-regulation of PVR from the cell surface, resulting in reduction of cell movement and proliferation. Involved in axon guidance by promoting contacts between the commissural axons and the floor plate cells (By similarity). Also involved in the formation of cell-cell junctions, including adherens junctions and synapses (By similarity). Promotes formation of checkerboard-like cellular pattern of hair cells and supporting cells in the auditory epithelium via heterophilic interaction with NECTIN1: NECTIN1 is present in the membrane of hair cells and associates with NECTIN3 on supporting cells, thereby mediating heterotypic adhesion between these two cell types (By similarity). Plays a role in the morphology of the ciliary body (By similarity).
Synonyms: CD113; PRR3; PVRL3; nectin-3; PPR3; PVRR3; DKFZP566B0846; CDw113
Tractability: Antibody: UniProt places it where antibodies can reach, with high confidence; its Gene Ontology location is reachable by antibodies, with high confidence; UniProt predicts a signal peptide or a membrane-spanning region. PROTAC: ubiquitination databases record sites on it.
Gene: Protein-coding gene on chromosome 3 (111,070,071 to 111,275,563, forward strand). Ensembl gene ENSG00000177707.
Subcellular location: Cell membrane; Postsynaptic cell membrane; Cell junction, adherens junction
Subcellular location (Human Protein Atlas): Cell Junctions; Cytosol
Pathways (Reactome):
Cell-Cell communication: Adherens junctions interactions; Nectin/Necl trans heterodimerization
Gene Ontology:
Molecular function: cell adhesion molecule binding; protein binding; cell adhesion mediator activity; identical protein binding; protein homodimerization activity
Biological process: cochlea morphogenesis; establishment of protein localization to plasma membrane; heterophilic cell-cell adhesion; homophilic cell-cell adhesion; cell adhesion; regulation of postsynapse assembly; symbiont entry into host cell
Cellular component: plasma membrane; adherens junction; apical junction complex; cell-cell junction; postsynaptic membrane; axon; cell-cell contact zone; dendrite; hippocampal mossy fiber to CA3 synapse; postsynaptic density membrane
Genetic constraint (gnomAD): Loss-of-function variants: 7 observed, 41.58 expected, observed/expected ratio (o/e) 0.17, 90% interval 0.095 to 0.32. The upper end of that interval is the gene's LOEUF score, 0.32, which puts it in group 1 of 6, group 1 being the genes least tolerant of losing a copy. Missense variants: 563 observed, 655.62 expected, observed/expected ratio (o/e) 0.86, 90% interval 0.8 to 0.92. Synonymous variants: 270 observed, 239.63 expected, observed/expected ratio (o/e) 1.13, 90% interval 1.02 to 1.25.
Homologues: Orthologues: chimpanzee NECTIN3 (100% identical), macaque NECTIN3 (99% identical), dog NECTIN3 (97% identical), rat Nectin3 (93% identical), guinea pig NECTIN3 (93% identical), rabbit NECTIN3 (89% identical), pig NECTIN3 (68% identical), mouse Nectin3 (68% identical), tropical clawed frog nectin3 (60% identical), zebrafish nectin3b (40% identical), Drosophila melanogaster Fas3 (15% identical). Paralogues in human: NECTIN1 (28% identical), NECTIN4 (24% identical), NECTIN2 (24% identical), PVR (19% identical), CADM3 (17% identical), CADM1 (17% identical), CADM2 (15% identical), CADM4 (14% identical), CD226 (12% identical), CD200 (11% identical), CRTAM (9% identical), NCR3 (7% identical), and 2 more.
Diseases named in the same sentence as NECTIN3 in open-access papers:
NECTIN3 is named in the same sentence as 45 diseases in open-access papers, as found by Europe PMC text mining. Sharing a sentence is not in itself a finding about the gene and the disease. The quoted sentences say what the papers report.
breast carcinoma (6 papers, 2013 to 2024). "In conclusion, it appears that Nectin family members have disparate expression in human breast cancer and that the aberrant expression of Nectin-3 is associated with metastatic disease." (PMID 24386110, 2013). "We found Nectin-3 and Nectin-4 to be reduced in breast cancer and associated with good prognosis and patient outcome." (PMID 24386110, 2013). "Meanwhile, Nectin-3 is downregulated in pancreatic adenocarcinoma and neuroendocrine tumors along with breast cancer." (PMID 36553083, 2022). "Sequential overlapping amplification via RT-PCR showed that the majority of breast cancer cell lines expressed the first domain of Nectin-3." (PMID 24386110, 2013). "This study aimed to ascertain the distribution of Nectins-1 to -4 in human breast cancer and the effect on junctional integrity of Nectin-3 modulation in human endothelial and breast cancer cells." (PMID 24386110, 2013). "There has not been, to date, a study examining the distribution and expression of all four Nectins in human breast cancer and further information on the roles of Nectin-3 have yet to be determined." (PMID 24386110, 2013). "It appears from these results that Nectin-3 is expressed as a truncated form in nearly all the human breast cancer cells analysed." (PMID 24386110, 2013). "Nectin-3 over-expression was induced in the human breast cancer cell line MDA-MB-231 and the human endothelial cell line HECV." (PMID 24386110, 2013). "Over-expression of Nectin-3 in human breast cancer cells resulted in a significantly reduced aggressive phenotype, cells that were less motile, less invasive, slower growing; however, these cells had increase TJ function." (PMID 24386110, 2013). "Nectin-3 may be a key component in the formation of cell junctions and a putative suppressor molecule to the invasion and metastases of breast cancer cells." (PMID 36553083, 2022). "Nectin-3 may be a key component in the formation of cell junctions and be a putative suppressor molecule to the invasion of breast cancer cells." (PMID 24386110, 2013). "Interestingly, increased confluency of human breast cancer cells resulted in increased transcript of Nectin-3." (PMID 24386110, 2013). "This study aimed to ascertain the distribution of Nectins in human breast cancer and to determine the role that Nectin-3 may have in regulating cell behaviour in human breast cancer and endothelial cells." (PMID 24386110, 2013). "Nectin-3 was only fully expressed in one breast cancer cell line (BT-482)." (PMID 24386110, 2013). "The expression and interaction of Nectin-3 in breast cancer and endothelial cells indicates that Nectin-3 may be a key component in the formation of cell junctions and be a putative suppressor molecule to the invasion of breast cancer cells." (PMID 24386110, 2013). "Nectin-3 (complete gene) was cloned into MDA-MB-231 and MCF-7 human breast cancer cells and expression confirmed using RT-PCR." (PMID 24386110, 2013). "We chose two breast cancer cells lines: MDA-MB-231, aggressive cells that only expressed the 386 bp region and MCF-7 cells, less aggressive and not expressing any regions of Nectin-3." (PMID 24386110, 2013).
lung adenocarcinoma (6 papers, 2013 to 2024). A carcinoma that arises from the lung and is characterized by the presence of malignant glandular epithelial cells. "Elevated expression of nectin-3 has been observed in various types of cancers, including lung adenocarcinomas, ovarian, and nasopharyngeal cancers." (PMID 37958883, 2023). "From the published data, we know that Nectin-3 expression is upregulated in lung adenocarcinomas, ovarian, and nasopharyngeal carcinomas." (PMID 36553083, 2022). "The membranous nectin-3 expression has been reported to be related to a poor prognosis in lung adenocarcinoma patients." (PMID 25690753, 2015). "However, in lung adenocarcinoma, it has been reported that membranous expression of Nectin-3 is an independent prognostic indicator." (PMID 24386110, 2013).
cognitive deficits (5 papers, 2017 to 2023). "Nectin-3, a cell adhesion molecule enriched in hippocampal neurons, has been implicated in stress-related cognitive disorders." (PMID 28872640, 2017). "Nectin3 is primarily located at adherens junctions in the hippocampus and plays an important role in synaptic plasticity and stress-related cognitive disorders." (PMID 36624454, 2023). "Nectin3 is an immunoglobulin-like CAM that is primarily involved in synaptic plasticity in the hippocampus and stress-related cognitive impairment." (PMID 36624454, 2023). "However, as AAV also infects dividing cells and non-dividing immature neurons, it is possible that nectin-3 knockdown disrupts the development and maturation of adult-born dentate granule cells, which may contribute to cognitive deficits." (PMID 28872640, 2017).
Anxiety (3 papers, 2014 to 2020). Intense feelings of nervousness, tension, or panic often arise in response to interpersonal stresses. "To examine the consequences of dorsal DG nectin-3 knockdown on anxiety and cognition in adult mice, we used the AAV-shNEC virus to suppress nectin-3 expression in both old and young DG neurons." (PMID 28872640, 2017). "Taken together, these results suggest that nectin-3 knockdown in the dorsal DG specifically impairs long-term hippocampus-dependent memory and mildly increases anxiety." (PMID 28872640, 2017). "In this study, we used adeno-associated virus (AAV) to suppress nectin-3 protein expression in both immature and mature DG neurons, and assessed the influences of DG nectin-3 knockdown on anxiety-related behavior and memory." (PMID 28872640, 2017). "In the light–dark box and elevated plus maze tests, the two groups of mice also performed similarly, indicating that reducing nectin-3 levels in newly generated DG neurons do not alter anxiety." (PMID 28872640, 2017). "We confirmed that the effects of nectin-3 OE were not due to altered physiological responses to the stress procedure (for example, body weight changes or corticosterone responses) or to changes in anxiety or locomotion." (PMID 25232752, 2014).
colorectal cancer (2 papers, 2023 to 2025). A primary or metastatic malignant neoplasm that affects the colon or rectum. "A statistically significant correlation was also found between the stage of advancement and nectin-3 expression, whose decline was accompanied by higher stages of colorectal cancer (CRC) advancement." (PMID 37958883, 2023). "Scientific reports on nectin-3 are also quite limited; however, the available data clearly indicate that nectin-3 influences tumor progression in colorectal cancer, ovarian cancer, and lung cancer, as well as has a significant prognostic impact on patient survival." (PMID 40244005, 2025).
microphthalmia (2 papers, 2015 to 2018). Congenital or developmental anomaly in which the eyeballs are abnormally small. "It is interesting that studies on mice lacking nectin-1 or nectin-3 showed a virtually identical ocular phenotype: microphthalmia." (PMID 29342882, 2018). "Studies on mice lacking nectin-1 or nectin-3 showed a virtually identical ocular phenotype: microphthalmia." (PMID 29342882, 2018).
ovarian carcinoma (2 papers, 2022 to 2025). A malignant neoplasm originating from the surface ovarian epithelium. "As an oncogene, Nectin-3 contributes to tumor progression in ovarian cancer." (PMID 36553083, 2022).
pancreatic adenocarcinoma (2 papers, 2015 to 2022). "Our present study showed that diffuse nectin-3 expression was associated with a good prognosis in pancreatic adenocarcinoma." (PMID 25690753, 2015). "In the case of pancreatic adenocarcinomas, reports on Nectin-3 expression are in line with previously cited studies, where diffuse expression in cancer cells was associated with a favorable prognosis." (PMID 36553083, 2022). "Most of the pancreatic adenocarcinoma cases demonstrated diffuse nectin-1 (median score: 3.0, mean score: 2.88) and nectin-3 (median score 3.0, mean score: 2.86) expression." (PMID 25690753, 2015).
pancreatic neuroendocrine tumor (2 papers, 2022 to 2023). Pancreatic endocrine tumor, also known as pancreatic neuroendocrine tumor (PNET), describes a group of endocrine tumors originating in the pancreas that are usually indolent and benign, but may have the potential to be malignant. "By contrast, the loss of expression of Nectins and Necls has been associated with a higher aggressiveness in several cancer cells e.g., Nectin-3 in pancreatic neuroendocrine tumor." (PMID 36553083, 2022).
tauopathy (2 papers, 2013 to 2014). Neurodegenerative disorders involving deposition of abnormal tau protein isoforms (tau proteins) in neurons and glial cells in the brain. "The decreased expression of Nectin-3 in the stratum lacunosum moleculare is an early marker of impaired transport, and eventual synaptic problems, caused by beginning tauopathy." (PMID 23704923, 2013). "These defects correlated with defective Nectin-3 levels, and fit the context of their cognitive defects, all predating the development of classical tauopathy defined by large intra-neuronal tau aggregates." (PMID 24498342, 2014). "The effect on expression of Nectin-3 in the SLM by the beginning tauopathy, prior to Tau aggregation, was both rapid and early." (PMID 23704923, 2013). "Among the CAMs analyzed, Nectin-3 expression was the most noticeably affected in the AD mouse models for tauopathy." (PMID 23704923, 2013). "Among the cell adhesion molecules analyzed, Nectin-3 expression was affected most and specifically in all mouse models with tauopathy." (PMID 23704923, 2013). "We recently identified a specific synaptic deficit of Nectin-3 in transgenic models for tauopathy." (PMID 24498342, 2014). "Here we studied the early functional and structural repercussions of tauopathy in the preclinical models, denoted Tau.P301L and biGT mice, from early age (3 months) when significant Nectin-3 expression was already lost, prior to the more classical tangle tauopathy." (PMID 24498342, 2014). "The function of Nectin-3 in the SLM, which according to our hypothesis must be located pre-synaptically, should now be subject to further analysis of eventual functional deficiency inflicted by protein Tau and tauopathy." (PMID 23704923, 2013). "The specific defect in the expression of Nectin-3 in the SLM of Tau.P301L mice led us to investigate whether Nectin-3 expression was affected in our other models for amyloid and tauopathy." (PMID 23704923, 2013). "Recently we reported that expression of Nectin-3, an important cell adhesion molecule (CAM) was compromised in the CA1 SLM of two transgenic models for tauopathy, carrying Tau.P301L without or with GSK3β." (PMID 24498342, 2014).
bone metastasis (1 paper, 2013). Transfer of a neoplasm from its primary site to bones. "Patients with ductal cancer, who remained alive and well, had higher levels of Nectin-3 than those who had poor outcome or bone metastasis (alive & well 390+/−151; poor outcome 324+/−154; bone metastasis 165+/−73.4, significance not reached)." (PMID 24386110, 2013).
colon cancer (1 paper, 2019). "NECTIN3 was associated with the proliferation of colon cancer cells, but this gene may be linked with the development of EOC." (PMID 30970615, 2019).
Ductal carcinomas (1 paper, 2013). "Ductal carcinomas had lower levels of Nectin-3 but not Nectin-4, (Nectin-3: ductal 1534+/−1177 versus other 2581+/−1699, p = 0.6; Nectin-4: ductal 0.30+/−0.15 versus other 0.022+/−0.021, p = 0.074)." (PMID 24386110, 2013).
endometriosis (1 paper, 2021). The growth of functional endometrial tissue in anatomic sites outside the uterine body. "We also identified putative inhibitory interactions between endometriosis immune cells and ectopic FBs rather than eutopic FBs, including KLRB1, TIGIT, and PDCD1, which were highly expressed by NK and T cells, and potentially bind to CLEC2D, NECTIN3, and FAM3C, which were expressed by FBs." (PMID 34233737, 2021).
Listeria infection (1 paper, 2025). "Listeria infection further led to the loss of Na+/K+-ATPase subunits ATP1A1 and ATP1B1, and loss of Afadin and Nectin-3, suggesting a disruption of junctional integrity and polarity upon cell invasion." (PMID 41510227, 2025).
lymph node metastasis (1 paper, 2015). "We performed a multivariate analysis that included the histological grade, lymph node metastasis and tumor size to assess the importance of the score of nectin-3." (PMID 25690753, 2015).
memory impairment (1 paper, 2017). "However, in the spatial object recognition test, mice with nectin-3 downregulated in new DG neurons showed memory impairments as indicated by significantly reduced object DI (t29=2.157, P=0.039; independent t-test)." (PMID 28872640, 2017).
metastatic disease (1 paper, 2013). "There was increased expression of Nectin-1/-2 in patients with metastatic disease, Nectin-3/-4 was reduced." (PMID 24386110, 2013).
multiple myeloma (1 paper, 2022). "The binding of CD155 and Nectin3 can induce the adhesion of multiple myeloma cells to bone marrow stromal cells." (PMID 36428703, 2022).
pancreatic cancer (1 paper, 2015). "Our results showed that the expression of nectin-3 in pancreatic cancer can be a prognostic factor." (PMID 25690753, 2015).